TYK2 (tyrosine kinase 2)
Diseases named in the same sentence as TYK2 in open-access papers (continued):
Sharing a sentence is not in itself a finding about the gene and the disease.
psoriasis (continued). "Deucravacitinib, an oral, selective, allosteric tyrosine kinase 2 inhibitor, is approved in Japan for adults with plaque, generalized pustular, and erythrodermic psoriasis who have inadequate response to conventional systemic therapies." (PMID 40304108, 2025). "Real-world evidence on the long-term effectiveness of deucravacitinib, a selective tyrosine kinase 2 inhibitor for psoriasis, remains limited, particularly in patients with different histories of systemic treatments." (PMID 39916637, 2025). "Selective TYK2 inhibitors such as deucravacitinib (recently approved in psoriasis) also block pathways downstream of type I IFN, IL-12, and IL-23, and represent an emerging class with relevance to interferon-driven disease." (PMID 41153754, 2025). "Crucially, our findings provide an underexplored regulatory mechanism of TYK2 inhibitor in psoriasis." (PMID 40038877, 2025). "Deucravacitinib, a selective oral TYK2 inhibitor, has been approved for the treatment of psoriasis and demonstrated high efficacy and a favorable safety profile." (PMID 41096715, 2025). "The use of biologic agents and TYK2 inhibitors in patients with psoriasis complicated by hematologic malignancies such as myelodysplastic syndrome (MDS) has been scarcely investigated to date." (PMID 40519492, 2025). "Deucravacitinib, a novel oral treatment option for moderate-to-severe psoriasis, is classified as a selective allosteric inhibitor of tyrosine kinase 2 (TYK2)." (PMID 40095854, 2025). "As a selective TYK2 inhibitor, deucravacitinib has demonstrated significant efficacy and a favorable safety profile, solidifying its role as a key treatment option in psoriasis." (PMID 40095888, 2025). "Deucravacitinib is an oral agent approved for moderate to severe psoriasis and selectively inhibits tyrosine kinase 2 (TYK2)." (PMID 40672022, 2025). "On top of that, on 9 September 2022, Bristol–Myers Squibb’s Deucravacitinib (oral) was approved in the US, ushering in a new era of targeted TYK2 treatment for psoriasis." (PMID 39861704, 2025). "This highlights a previously overlooked role of TYK2 in modulating KC behaviour during psoriasis pathogenesis." (PMID 40038877, 2025). "Tyrosine kinase 2 (TYK2)‐dependent cytokine signalling is integral to the pathogenesis of psoriasis." (PMID 40038877, 2025). "This role makes TYK2 inhibition therapeutically relevant for conditions like psoriasis and other immune-mediated diseases driven by IL-12 and IL-23." (PMID 40095888, 2025). "By selectively inhibiting TYK2, deucravacitinib disrupts these signaling pathways, reducing cytokine production and alleviating psoriasis symptoms." (PMID 40095854, 2025). "While BMS‐986165, a highly selective TYK2 inhibitor, has recently been approved for oral treatment of psoriasis, its therapeutic potential via topical application remains unexplored." (PMID 40038877, 2025). "TYK2 is a key mediator in the signaling of cytokines central to psoriasis pathogenesis, including IL-23, IL-12, and type I interferons." (PMID 40095854, 2025). "A meta-analysis identified 11 susceptibility loci shared between psoriasis and IBD, but only four—IL23R, IL12B, REL, and TYK2—showed strong overlap for CD, suggesting weaker genetic linkage compared with UC." (PMID 41153620, 2025). "TYK2 inhibitors in phase II development for psoriasis include ESK-001 (Alumis, Inc., San Francisco, CA, USA) and BMS-986322 (Bristol Myer’s Squib, New York, NY, USA), a structural variant of deucravacitinib." (PMID 38258121, 2024). "In conclusion, we focused on advanced TYK2 inhibitor to develop a new ROS-responsive topical formula of deucravacitinib based on PEPS micelles with inherent antioxidative capacity for psoriasis treatment." (PMID 38799436, 2024). "In psoriasis, TYK2 plays a key role in disease pathogenesis, mediating IL-12, IL-23, and IFN-α signaling and promoting the development of the Th1 and Th17 cell lines." (PMID 38258121, 2024).
psoriasis (continued). "Deucravacitinib selectively binds to the regulatory domain of tyrosine kinase 2 (TYK2), an intracellular kinase that mediates signaling of interleukin-23 and other immune molecules implicated in the pathogenesis of psoriasis." (PMID 39430635, 2024). "The introduction of the highly selective TYK2 inhibitor, deucravacitinib, was a great stepping stone for the treatment of psoriasis, providing effective treatment with an improved safety profile." (PMID 38731900, 2024). "Other reports performed on mouse models of psoriasis have concluded that TYK2 can slow the progression of psoriasis." (PMID 38793117, 2024). "The first small molecule TYK2 inhibitor was approved by the FDA in 2022 for the treatment of psoriasis, with additional agents under investigation for use in other autoimmune conditions." (PMID 38766166, 2024). "The TYK2/JAK1 signaling cascade is implicated in dendritic cell migration and activation in inflammatory disease processes, such as psoriasis and type 1 diabetes." (PMID 38912581, 2024). "This suggests that targeting TYK2 in IL-12/23–driven diseases such as psoriasis is more effective, while additionally avoiding JAK1,2,3 inhibitor hematopoietic safety concerns." (PMID 39403378, 2024). "Deucravacitinib is the first TYK2 inhibitor to be approved for psoriasis, binding to the enzyme’s allosteric site (JH2 domain) and demonstrating high selectivity against other JAK isoforms." (PMID 38258121, 2024). "Deucravacitinib, the first allosteric Tyk2 inhibitor, was approved for treating moderate to severe psoriasis by the FDA in September 2022 and soon later by the EMA and the Japanese regulatory agency, among others." (PMID 38399292, 2024). "Second-generation JAK inhibitor deucravacitinib is a highly selective TYK2 inhibitor that targets key inflammatory pathways involved in psoriasis pathogenesis." (PMID 38793117, 2024). "This form of evidence has been instrumental in development of statins and cementing support for TYK2 as target in the treatment of psoriasis." (PMID 38852887, 2024). "TYK2 is part of the JAK-STAT signaling pathway that mediates the expression of several drivers of psoriasis, such as Type I IFNs, IL-12, and IL-23, making TYK2 an integral part of inflammation and immune response regulation." (PMID 38303723, 2024). "The JAK-STAT and TYK2 pathways play an important role in the signal transmission of cytokines in psoriasis, with different combinations of JAKs mediating different cytokine signaling." (PMID 38008779, 2023). "Extensive molecular profiling of 267 psoriasis patients undergoing deucravacitinib revealed that TYK2 inhibition restores the epidermal expression of pathologic hallmarks of psoriasis, such as K16, CD3, and Ki-67+ cells after 3 months of treatment." (PMID 37108251, 2023). "Tyk2-mediated signal transduction lies at the crossroads of multiple pathogenic cytokines, and its specific inhibition may provide effective treatment with comorbid IMIDs, such as psoriasis, psoriatic arthritis, spondyloarthropathies, and inflammatory bowel disease." (PMID 36834806, 2023). "JAK and TYK2 inhibitors, with exemplars of tofacitinib, baricitinib, and deucravacitinib, respectively, display promising results in reducing psoriasis symptoms and improving skin clearance." (PMID 37108251, 2023). "Deucravacitinib has become the first Tyk2 inhibitor approved for moderate to severe psoriasis treatment, but potential indications in other IMIDs are multiple and the therapeutic potential of Tyk2 inhibitors are not limited to psoriatic disease." (PMID 36834806, 2023). "More long-term studies are necessary to learn the efficacy and safety of PDE4 and TYK2 inhibitors for psoriasis when being used for a long period of time." (PMID 37334353, 2023). "PF-06826647 is another TYK2 inhibitor currently in Phase II trials for moderate to severe psoriasis." (PMID 38239345, 2023).
psoriasis (continued). "Deucravacitinib is the first oral selective tyrosine kinase 2 (TYK2) inhibitor responsible for the signaling of IL-23 and other cytokines involved in the pathogenesis of psoriasis." (PMID 38203337, 2023). "Oral TYK2 inhibitors demonstrated satisfactory performance in treating psoriasis, surpassing apremilast at certain doses." (PMID 37334353, 2023). "We found consistent evidence supporting the efficacy of TYK2 inhibitors for psoriasis and its related disorders." (PMID 36842216, 2023). "This study supports TYK2 inhibitor as a potential treatment for psoriasis and several other autoimmune diseases." (PMID 36842216, 2023). "Genetic linkage has related dysfunction of Tyrosine kinase 2 (Tyk2)—the first member of the Jak family that was described—to protection from psoriasis." (PMID 36834806, 2023). "Oral small-molecule PDE4 and TYK2 inhibitors appear effective and safe in treating psoriasis, but they work through different mechanisms of action." (PMID 37334353, 2023). "It is on the market and has been reported to block key molecules in the pathogenesis of psoriasis, including TYK2." (PMID 37845748, 2023). "In September 2022, deucravacitinib became the first Tyk2 inhibitor approved for the treatment of moderate-to-severe psoriasis." (PMID 36834806, 2023). "Several additional TYK2 inhibitors, including brepocitinib and ropsacitinib, were also under development for treating psoriasis." (PMID 37334353, 2023). "Mutations in genes coding for Tyk2, Jak2, and STAT3 have been found to be associated with psoriasis." (PMID 37628670, 2023). "The TYK2, a JAK family gene, has been associated with psoriasis susceptibility genes and loss of function mutation is associated with various cytokine signaling defects that are implicated in psoriasis pathogenesis." (PMID 35265634, 2022). "The effect is similar as the most advanced clinical TYK2 pseudokinase ligand Deucravacitinib and more potent than the TYK2 kinase inhibitor that entered Phase II clinical development against moderate-to-severe psoriasis, Ropsacitinib." (PMID 35693820, 2022). "Another selective TYK2 inhibitor, PF-06826647, is also being tested in moderate-to-severe psoriasis in an ongoing phase II clinical trial (NCT03895372)." (PMID 35265634, 2022). "The efficacy of deucravactinib in treating plaque psoriasis is attributed to the selective inhibition of TYK2, a downstream mediator of proinflammatory signalling pathways critical to psoriasis." (PMID 35747941, 2022). "Deucravacitinib (BMS-986165) is a selective TYK2 JAK inhibitor under development for psoriasis, with promising results." (PMID 34209234, 2021). "BMS-986165 is a selective Tyk2 inhibitor that have shown efficacy in a Phase II clinical trial for psoriasis treatment, and it is being studied in systemic lupus erythematosus, psoriatic arthritis, and inflammatory bowel diseases." (PMID 32906785, 2020). "Consistent with this concept, recent findings using an oral TYK2 inhibitor have demonstrated beneficial effects in treatment of adult subjects with psoriasis." (PMID 30740104, 2019). "Nevertheless, IL-23 signals via tyrosine kinase 2 (Tyk2) blockers for psoriasis support the idea of a therapy effect via IL-23 alone [51••, 53]." (PMID 29846815, 2018). "Our investigation of alleles at the low end of the frequency spectrum with variant aggregation tests has expanded our understanding of the allelic architecture of psoriasis risk at the IFIH1 and TYK2 loci." (PMID 28973304, 2017). "The PheWAS results for the variant encoding p.Ile684Ser in TYK2 (which we noted was working through the ICAM1 gene) highlighted a known risk association with IBD and a protective association for psoriasis." (PMID 29091937, 2017). "TYK2 is integral to the IL-23/IL-17 axis, a key driver of psoriasis pathogenesis." (PMID 40095854, 2025).
psoriasis (continued). "Indeed, BMS‐986165 (Deucravacitinib) is a selective potent oral TYK2 inhibitor currently used for psoriasis treatment, and two other TYK2 inhibitors (TAK‐279, VTX958) are under development for psoriasis treatment." (PMID 39835539, 2025). "Similarly, deucravacitinib, an allosteric selective tyrosine kinase 2 (TYK2) inhibitor recently approved for psoriasis, has demonstrated potential in a small case series involving five PPP patients." (PMID 40429269, 2025). "As a member of JAK family, tyrosine kinase 2 (TYK2) mainly participates in the signalling transduction of type I interferons and IL‐12/IL‐23, which are pivotal in driving DC and Th cell hyperactivation in psoriasis." (PMID 40038877, 2025). "This study reveals a novel therapeutic potential for selective TYK2 inhibitor in topical manner on psoriasis therapy, which might prompt the development of topical treatment for psoriasis." (PMID 40038877, 2025). "Genetic loss of TYK2 function has been associated with a lower risk of developing immune‐mediated diseases, including psoriasis, without increased safety risks." (PMID 38268101, 2024). "Deucravacitinib is an tyrosine protein kinase 2 (TYK2) inhibitor to downregulate the IL-23/Th17 and type I interferon pathway, which has been approved by the Food and Drug Administration for oral therapy of psoriasis." (PMID 38799436, 2024). "Researchers have identified STAT3, TYK2, IL23A, and IL23R as susceptibility factors for psoriasis." (PMID 39296901, 2024). "In a mouse model of imiquimod-induced psoriasis-like dermatitis, IL-17 and IL-22 secreted from γδ T cells and Th17 upon IL-23 stimulation were involved in skin inflammation and keratinocyte activation, which were improved by TYK2 inhibitor treatment." (PMID 38351043, 2024). "Current research is focused on the development of oral therapies with improved efficacy and safety compared with available alternatives, as exemplified by deucravacitinib, the first oral allosteric Tyk2 inhibitor approved for the treatment of moderate to severe psoriasis in adults." (PMID 38399292, 2024). "New molecules are currently under investigation for the treatment of psoriasis, such as deucravacitinib, an oral selective inhibitor that binds to the regulatory domain of TYK2, brepocitinib (PF-06700841) and PF-06826647 that bind to the active site in the catalytic domain." (PMID 38892802, 2024). "Furthermore, Tyk2 deficiency protects mice from severe inflammation in Systemic Lupus Erythematosus (SLE), arthritis and psoriasis." (PMID 38683377, 2024). "Furthermore, the first drug targeting the pseudokinaseATP pocket, TYK2 inhibitor deucravacitinib, has been approved forthe treatment of psoriasis." (PMID 38843875, 2024). "Deucravacitinib is an oral tyrosine kinase 2 (Tyk2) inhibitor effective for psoriasis treatment." (PMID 39830543, 2024). "Among Jak inhibitors, allosteric Tyk2 inhibitors may be the most promising class for oral treatment of moderate to severe psoriasis, with the best efficacy/safety ratio and negligible changes in laboratory parameters." (PMID 38399292, 2024). "Deucravacitinib is an oral, first-in-class, selective tyrosine kinase-2 (TYK-2) inhibitor and member of the Janus kinase family approved for the treatment of moderate-to-severe plaque psoriasis, and, in Japan, also for pustular and erythrodermic psoriasis." (PMID 38883165, 2024). "A self‐locking MN patch for psoriasis delivers TYK2 inhibitor to target skin‐originated inflammation and modulate local immune microenvironment, while simultaneously releases Cal for sustained anti‐proliferative effects on persistent hyperproliferative lesions." (PMID 39473371, 2024). "This can be explained by the implication of Tyk2 in multiple pathways related to psoriasis." (PMID 36834806, 2023).
psoriasis (continued). "Conversely, signaling of IL-12 and especially IL-23, which is pathogenetically related to psoriasis, is mediated by Tyk2/Jak2; selective inhibition of Tyk2 avoids interference with multiple Jak2 mediated pathways and potential hematopoietic or thromboembolic adverse events." (PMID 36834806, 2023). "Hence, multiple Tyk2 inhibitors are being evaluated for the treatment of inflammatory diseases such as psoriasis, psoriatic arthritis, hidradenitis suppurativa, inflammatory bowel disease, dermatomyositis, and SLE." (PMID 36834806, 2023). "On the other hand, the future seems bright for selective Tyk2 inhibitors that maintain the safety profile of deucravacitinib and provide improved efficacy in psoriasis—perhaps comparable to that of biologic agents targeting the regulatory cytokine IL-23—and in other potential indications." (PMID 36834806, 2023). "Finally, the newest approved drug for psoriasis, deucravactinib, functions to inhibit tyrosine kinase 2 (TYK2), a member of the JAK family." (PMID 37569685, 2023). "However, relatively few clinical trials on autoimmune diseases except psoriasis hinder the assessment of the effectiveness of TYK2 inhibitor treatment on autoimmune diseases." (PMID 36842216, 2023). "The genes associated with psoriasis that encode players in the JAK-STAT pathway are STAT4 and TYK2." (PMID 37569685, 2023). "Genome-wide association studies (GWAS) have established a relationship between the JAK-STAT pathway and IMIDs, For example, JAK2, Tyk2, STAT1, STAT3, STAT4, and IBD; TyK2, TAT1, SLE; TyK2, STAT4, RA; and TyK2, STAT3, and psoriasis are closely linked to the JAK-STAT pathway." (PMID 37351513, 2023). "However, no previous articles evaluated the benefit and risk profile of TYK2 and PDE4 inhibitors in psoriasis." (PMID 37334353, 2023). "However, the tissue specific gene expression analysis only validated the inverse effects of genetically proxied TYK2 inhibition on hypothyroidism and psoriasis and its related disorders." (PMID 36842216, 2023). "As a critical intracellular component of the IL12, IL23 and type I IFN cytokine cascades, TYK2 plays pivotal roles in autoimmune disorders including psoriasis (Ps), inflammatory bowel disease (IBD), systemic lupus erythematosus (SLE), lupus nephritis, multiple sclerosis (MS), etc.." (PMID 35693820, 2022). "This might provide a rationale for potential therapeutic utility in T1D of more potent inhibitors of the IL-23 pathway, in current or planned use in psoriasis and inflammatory bowel disease, such as guselkumab, risankizumab, or TYK2 inhibition." (PMID 35072168, 2022). "Interestingly, a recent study describes a TYK2 splice variant (Rs2304256) that is protective against SLE, T1D and psoriasis." (PMID 34439323, 2021). "BMS-986165 was recently reported as an effective therapeutic for psoriasis in phase II trials, and has been shown to inhibit the pseudokinase domain of TYK2 to provide a therapeutic effect against type I IFN– and IL-12–dependent autoimmune disease models in vivo." (PMID 32149730, 2020). "Brepocitinib (PF-06700841) is a Tyk2/Jak1 inhibitor that is being tested in psoriasis." (PMID 32906785, 2020). "We identified that the Ile684Ser variant within the TYK2 gene, which may act through the ICAM1 gene, is associated with many traits including psoriasis, Crohn’s disease, and infections, and may suggest integrins and their receptors as potential drug targets." (PMID 29091937, 2017). "However, increased TYK2 expression has been scarcely reported and TYK2 downregulated mRNA has been previously observed in psoriasis." (PMID 27711196, 2016). "The importance of TYK2 in inflammatory diseases is based on genetic polymorphisms and murine experiments with knockout mice demonstrating its role in IL22 and IL23-mediated signaling in psoriasis." (PMID 27711196, 2016). "Conversely, TYK2 and pTYK2 was underexpressed in the epidermis of psoriasis, LP, CLE and PG." (PMID 27711196, 2016).